AGPS (alkylglycerone phosphate synthase)
Diseases named in the same sentence as AGPS in open-access papers (continued):
Sharing a sentence is not in itself a finding about the gene and the disease.
cancer (continued). "Inactivation of AGPS lowers ether lipid levels and impairs cancer pathogenicity." (PMID 38383581, 2024). "Studies have revealed that AGPS knockdown could decrease the levels of several ether lipid species, arachidonic acid, LPAe, and prostaglandins in cancer cells." (PMID 34621897, 2021). "Furthermore, protection from DGLA-induced ferroptosis was conserved in mammalian systems, as cancer cells co-treated with ZINC-69435460 (AGPS inhibitor) and DGLA were significantly sensitized to cell death, even more so than DGLA treated cancer cells alone." (PMID 33672292, 2021). "Targeting AGPS could therefore be of potential benefit to increase MM cell death, since multiple AGPS inhibitors are under development in other cancers." (PMID 32500036, 2020). "According to our results, the increase in PE plasmalogens could be explained by overexpression of the key plasmalogen synthesis enzymes, FAR1, FAR2, and AGPS, in all cancer cell lines." (PMID 32443825, 2020). "Western blot analysis showed that FAR1, FAR2, and AGPS protein expression was consistently enhanced in all cancer cell lines compared to primary cells, although these differences were statistically different in all tumor cell lines simultaneously only for FAR1." (PMID 32443825, 2020). "Indeed, increased ether lipids are correlated with more aggressive cancers, and knockdown of AGPS in a variety of cancer cell lines results in impaired pathogenicity." (PMID 28523433, 2018). "The studies indicated that AGPS may serve as an attractive therapeutic target for combatting malignant human cancers, through altering the landscape of oncogenic signaling lipids that drive cancer aggressiveness." (PMID 29514688, 2018). "Additionally, combined treatment with AGPSi and chemotherapy + PE O– resulted in a further reduction in colony area by approximately 40% and 70%, respectively, confirming that AGPS inhibitor treatment sensitises cancer cells to the cytotoxic effects of cisplatin and paclitaxel." (PMID 39700026, 2024). "Our study also highlights the important role of the MEK/ERK/SRF pathway in driving ferroptosis sensitivity and regulating the expression of AGPS and AGPAT3 in cancers." (PMID 38383581, 2024). "Therefore, these two compounds could be used to reduce the enzymatic function of the AGPS enzyme in the SARS-CoV-2 infected lung cells (in a similar manner as in the cancer cells), which would result in a hamper of the viral replication, while allowing the viability of the non-infected cells." (PMID 34099831, 2021). "Nevertheless, several different cancer cells get sensitized to evasion from ferroptosis by lowering plasmalogens where expression of ATP8B2 mRNA is increased, though both protein and mRNA expressions of AGPS and TMEM189 are reduced." (PMID 35832735, 2022). "In addition, suppression of AGPS activity in cancer cells such as MDA-MB-231 expressing a higher level of AGPS reduces cell proliferation, although the precise mechanism underlying the suppression of cell growth by the inhibition of AGPS activity remains unknown." (PMID 35832735, 2022). "Interestingly, AGPS was overexpressed in Colo 201 not only compared to primary cells but also, and importantly, compared to all the in situ cell lines, that is, SW480, LS174t, and HT29 cancer cells (1.5- to 5-fold higher)." (PMID 32443825, 2020). "By contrast, AGPS inactivation, which depletes both 1-O-alkyl-lipids and 1-O-alkenyl-lipids, was sufficient to restore growth of GPX4−/− tumors, suggesting that the spontaneous downregulation of AGPS contributes to the observed emergence of ferroptosis resistance in the carcinoma cell model." (PMID 33149249, 2020).
tumor (11 papers, 2016 to 2024). "Alkylglycerone phosphate synthase (AGPS) is a key enzyme in the synthesis of ether esters and plays a vital role in maintaining the morphology and pathogenic properties of tumor cells." (PMID 34621897, 2021). "To further verify the role of AGPS in PCa, we performed a subcutaneous transplantation tumor model using severely immunodeficient mice and found that the tumor progressed by AGPS knockdown." (PMID 38200609, 2024). "We subsequently investigated the role of AGPS in cell invasion and adhesion, other key cellular mechanisms promoting tumor aggressiveness." (PMID 38642894, 2024). "Using narrow-down analysis, six tumor antigens (AGPS, NRAS, MTDH, PANX1, NOX4, and PPARD) were found to be related to better prognoses as well as the infiltration of antigen-presenting cells in LUAD." (PMID 38331967, 2024). "In contrast, there are very few reports related to the role of AGPS in peroxisome production and tumor progression." (PMID 38200609, 2024). "Subsequently, we selected 89 pairs of PCa tumor and normal tissues for IHC staining and found that the positive rate of AGPS was significantly lower in PCa tumors than in normal tissues." (PMID 38200609, 2024). "For the two other epitopes identified by MS as presented on KADA tumor MHC-I (AGPS, ENC1), we could unequivocally demonstrate that these epitopes were not recognized by the autologous TIL." (PMID 31921104, 2019). "Therefore, we speculate Larotrectinib could promote the accumulation of AGPS and exert a positive effect on ferroptosis inducers in tumor therapy." (PMID 38200609, 2024). "In this study, AGPS and AGPAT3 were found to be expressed at higher levels in GC tissues, especially in CagA+ H. pylori-infected tumor tissues, than in normal tissues." (PMID 38383581, 2024). "Alkylglycerone phosphate synthase (AGPS) is a key enzyme in the synthesis of ether lipids to promote peroxisome formation and increase the sensitivity of tumor cells to ferroptosis." (PMID 38200609, 2024). "Considering the interaction between tumor antigens and APCs, these potential antigens were further screened through the TIMER database where it was found that AGPS, NRAS, MTDH, PANX1, NOX4, and PPARD genes were positively correlated with different APCs." (PMID 38331967, 2024). "This is exemplified by the AGPS and ENC1 neoepitopes that were detected by MS as being presented on the tumor lines." (PMID 31921104, 2019). "The comparison of 20 pairs of PCa tumor and normal tissues demonstrated that AGPS mRNA expression was not very significantly different between the tumor tissues and normal tissues, which coordinated with the results in the cell lines." (PMID 38200609, 2024). "On the contrary, the CCK8 and clone formation assays indicated that AGPS overexpression inhibited tumor cell growth, and concomitant overexpression of MDM2 resulted in significantly higher PCa cell activity as compared to the experimental group overexpressing AGPS alone." (PMID 38200609, 2024). "In our study, the majority of neoepitopes that could activate TIL had not gained binding affinity to HLA-A2 compared to the corresponding wild-type peptide; only for the AGPS and MYLIP peptides from the KADA tumor was an increased binding observed, as confirmed by HLA-A2 stabilization assays." (PMID 31921104, 2019).
infection (3 papers, 2016 to 2023). The state of being infected such as from the introduction of a foreign agent such as serum, vaccine, antigenic substance or organism. "This may indicate that AGPs are causing a dampened inflammatory status under basal physiological conditions, but allows a robust inflammatory response under conditions of infection." (PMID 27929072, 2016). "Four AGPS genes were identified and increased after infection in CBH with maximum levels at 1 d (AGPS1-1, 1-2, and 1-3) and 5 d (AGPS1-4)." (PMID 37701805, 2023). "AGPS gene levels decreased after infection in G28, with the lowest levels at 3 d (AGPS1-1 and 1-2) and 7 d (AGPS1-3 and 1-4)." (PMID 37701805, 2023). "This suggests that in addition to immune-modulation, AGPs may protect the host from metabolic deregulation that occurs following infection." (PMID 27929072, 2016). "Infected (CR+) but not uninfected (CR−) mice that that were not administered AGPs exhibited a lower body weight (p = 0.016) and feed consumption (p = 0.026) at peak infection (i.e. ca. 7 days post inoculation (p.i.))." (PMID 27929072, 2016).
infectious disease (1 paper, 2025). A disorder directly resulting from the presence and activity of a microbial, viral, or parasitic agent in humans. "Furthermore, the mode of action of AGPs on the development of infectious diseases cannot be solely attributed to their direct antibacterial properties, implying that other AGPs may exert other effects beyond their antimicrobial action." (PMID 40735741, 2025).
AGPS also shares sentences with these, for which no sentence is quoted: cognitive decline (4 papers); Alzheimer disease (1); Anxiety (1); Cerebellar atrophy (1); colon cancer (1); glioblastoma (1); gram-positive bacterial infections (1); Intellectual disability (1); invasive breast carcinoma (1); monocytopenia (1); neutropenia (1); osteosarcoma (1); pancreatic cancer (1); rhizomelic chondrodysplasia punctata type 1 (1); rhizomelic chondrodysplasia punctata type 3 (1); steatosis (1); thalassemia (1).